CDC25C (cell division cycle 25C)
Diseases named in the same sentence as CDC25C in open-access papers (continued):
Sharing a sentence is not in itself a finding about the gene and the disease.
lung carcinoma (17 papers, 2010 to 2025). "LicoA induces G2/M-phase cell cycle transition by decreasing the expression of MDM2, cyclin B1, cdc2, and cdc25c proteins, and it causes apoptosis by upregulating the activation of proapoptotic caspase-3 and PARP cleavage via ER stress in human lung cancer." (PMID 40002335, 2025). "Recently, PUF60 has been reported to be involved in promoting cell cycle and lung cancer progression by regulating alternative splicing of CDC25C." (PMID 40411278, 2025). "Survival analysis was conducted using the TCGA database to determine the correlation between CDC25C expression and lung cancer prognosis." (PMID 35574406, 2022). "TRIM59 has a high expression level in a variety of lung cancer cell lines, while knockdown of which can affect the expression of cyclins (including CDC25C and CDK1), thereby enhancing the proliferative and migratory abilities of lung cancer cells." (PMID 35912155, 2022). "SiRNA-induced knockdown of TRIM59 significantly inhibited the proliferation and migration of lung cancer cells by increasing the expression of a number of cell cycle proteins including CDC25C and CDK136." (PMID 28211536, 2017). "Mao demonstrated that the expression of the CDC25C gene affects the invasion and migration of lung cancer cells through the study and analysis of scRNA-seq data, suggesting it may play a crucial role in the EMT pathway." (PMID 39144829, 2024). "First, to investigate whether CDC25C was differentially expressed between lung cancer and normal tissue, LUAD and lung squamous carcinoma (LUSC) RNA-seq data were downloaded from TCGA." (PMID 35574406, 2022). "Many studies have shown that CDC25C is highly expressed in lung cancer." (PMID 36408135, 2022). "Through reducing CDC25C and CDC2 protein levels, the heat shock protein 90 (HSP90) inhibitor is implicated in antiproliferative activity and tumor progression in lung cancer cells and thus can be applied for the treatment of lung cancer." (PMID 31885751, 2019). "In lung cancer cells, CUDC-907 initiated G2/M phase arrest through reducing the expression of cell cycle regulatory proteins as Cdc25C, CdC2, and Cyclin B1, and by elevating p21 protein level." (PMID 41148814, 2025). "In this study, we obtained eight lung cancer-related genes (CDC25C, TWIST1, HIF1A, DNMT1, PARP1, CDKN1A, CCNB1, and BIRC5) as seed nodes, using an RWR algorithm analysis to prioritize lung cancer related genes." (PMID 33193600, 2020).
hepatocellular carcinoma (14 papers, 2011 to 2026). A malignant tumor that arises from hepatocytes. "TCTP and CKS2 expression patterns are linked through the TCTP/CDC25C/CDK1 pathway, which was shown to be dysregulated in hepatocellular carcinoma." (PMID 40809150, 2024). "The present study revealed that the induction of G2/M phase cell cycle arrest by OPD was correlated with the regulation of Chk1-mediated G2/M checkpoint proteins, including cdc25c/cdc2 and cdc2/cyclin B1 complex pathways, in hepatoma cells." (PMID 31979361, 2020). "Dihydromyricetin, a flavonoid commonly found in grapes, berries, vegetables, herbs, and other plants, induces G2/M phase cell cycle arrest of hepatocellular carcinoma cells through the Chk2/Cdc25C pathway." (PMID 29734760, 2018). "S. nigrum L. (Long-Kui) polyphenolic extract induces apoptosis and G2/M cell cycle arrest by down-regulating CDC25A, CDC25B and CDC25C in hepatoma cells." (PMID 26828466, 2016). "In conclusion, costunolide specifically arrests cell cycle at mitosis accompanied by modulation of Chk2/Cdc25c/Cdk1/cyclin B1 signaling and enhancement of radioresponse in human hepatoma HA22T/VGH cells." (PMID 21624128, 2011). "In addition, previous reports have demonstrated that downregulation of cdc25C occurred in parallel with G2/M arrest of hepatoma and glioblastoma cells induced by Helle and Areno." (PMID 34513690, 2021). "In hepatocellular carcinoma, CHEK1 activates CDC25C through phosphorylation, relieving CDK1 inhibition and promoting the G2/M phase transition, thus accelerating proliferation." (PMID 41564103, 2026). "For example, CDC25C mRNA was shown to be elevated in hepatocellular carcinomas relative to nontumorigenic liver tissue and high CDC25C mRNA levels predicted poor outcomes." (PMID 36830899, 2023). "For instance, in hepatocellular carcinoma (HCC) cells, Romidepsin has been found to induce apoptosis and G2/M phase arrest through the activation of JNK/c-Jun/caspase-3 and Erk/cdc25C/cdc2/cyclinB pathways, respectively." (PMID 38822399, 2024).
prostate carcinoma (13 papers, 2011 to 2025). A carcinoma that arises from epithelial cells of the prostate gland. "In prostate carcinoma, expression of alternative splicing variants of the CDC25C isoform are also increased, and up-regulation of expression levels is associated with the recurrence of prostate-specific antigen." (PMID 32518522, 2020). "Studies have shown that PLK1 and CDC25C are overexpressed in prostate cancer, and PLK1 expression is also associated with high tumor grade." (PMID 32518522, 2020). "Studies in recent years have shown that the expression of CDC25C in prostate cancer is up-regulated compared to normal prostate organization, and the dephosphorylated form is nearly the only form existent." (PMID 32518522, 2020). "CHEK1 contributes to CDC25C-mediated Docetaxel resistance and can also be a therapeutic target in prostate cancer." (PMID 32503434, 2020). "For the first time, our study elucidated a unique molecular mechanism of action of SD-208 through induction of p21 along with increased phosphorylation of Cdc2 and Cdc25C, which contributed to G2/M arrest in prostate cancer cell proliferation." (PMID 25747583, 2015). "To further demonstrate the role of CDC25C, we used pharmacological inhibitors of PLK1 and CHEK1, in our LZTS1-deficient Docetaxel resistant prostate cancer cells." (PMID 24525428, 2014). "Our data provide a mechanistic explanation of elevated Cdc25C protein levels on clinical prostate carcinomas and its role in PCa cell proliferation." (PMID 23637932, 2013). "In contrast to these findings, overexpression of wild type Cdc25C as well as expression of protein mutated at key cysteine residues failed to rescue prostate cancer cells from DATS-induced G2/M arrest suggesting a dispensable role of Cdc25C in this model." (PMID 28788092, 2017). "Interestingly, PLK1 and CDC25C are overexpressed in prostate cancer, and PLK1 expression correlates with high tumor grades." (PMID 24525428, 2014). "Since altered cell cycle is a hallmark of human cancers, we investigated androgen regulation of Cdc25C protein in human prostate cancer (PCa) cells, including androgen-sensitive (AS) LNCaP C-33 cells and androgen-independent (AI) LNCaP C-81 as well as PC-3 cells." (PMID 23637932, 2013). "In prostate carcinomas, Cdc25C and its spliced forms are upregulated at the mRNA and protein level." (PMID 23637932, 2013). "SHCBP1 was found to enhance prostate cancer cell development, metastasis, and mitosis, with the SHCBP1—polo‐like kinase 1 (PLK1)—CDC25C axis playing a key role in promoting tumorigenesis." (PMID 39949984, 2025). "CDC25C, CDCA5, TOP2A, and CENPU, genes whose expression levels were strongly correlated to CENPA expression in prostate cancer tissue, were all notably down-regulated with CENPA depletion, as well as bound by CENPA." (PMID 32371391, 2020). "In prostate cancer cells, SFN-induced DNA damage involved the Chk2-mediated phosphorylation of protein phosphatase Cdc25C." (PMID 22247744, 2011). "This notion was in line with a previous study that demonstrated KDM5D was involved in the regulation of ATR-dependent DNA damage repair of prostate cancer as shown by increasing CHK1 and cell division cycle 25C phosphatase (CDC25c) protein expression in response to KDM5D knockdown." (PMID 36982384, 2023).
bladder cancer (11 papers, 2013 to 2024). "By extending our finding to clinical data sets of approximately 400 patients with bladder cancer, we confirmed an association of CDC25C expression with poor survival in bladder cancer patients." (PMID 27775025, 2016). "Importantly, we found CDC25C overexpression to be a key feature of the BTC phenotype and show that CDC25C expression is an independent risk factor for death after surgery in clinical bladder cancers." (PMID 27775025, 2016). "Previous experiments with human lung and bladder cancer cells have confirmed that LicA can cause G2/M phase arrest by inhibiting CDC2, CDC25C, cyclin A, and cyclin B expression." (PMID 37238935, 2023). "In bladder cancer cells treated with nimbolide, the G2/M phase cell cycle was arrested via the checkpoint kinase 2 (Chk2)/Cdc25C and Chk2/p21WAF1-related cyclin B1/Wee1 pathway." (PMID 33996570, 2021). "Treatment with nimbolide decreased the protein levels of Cdc25c, Cdc2, and cyclin B1 and increased the expression of Wee1 and p21WAF1 in bladder cancer cells." (PMID 31391858, 2019). "We also report the clinical significance of CDC25C overexpression in bladder cancer as a determinant of poor prognosis." (PMID 27775025, 2016). "Immunohistochemical analysis of CDC25C protein expression using a human bladder cancer tissue microarray demonstrated a spectrum of nuclear CDC25C expression ranging from highly expressed in nearly all cells to limited expression in few cells." (PMID 27775025, 2016). "We found a step-wise increase in CDC25C expression from normal bladder mucosa to bladder mucosa surrounding cancer and finally to primary bladder cancers." (PMID 27775025, 2016). "Moreover, nimbolide treatment increased Cdc25c phosphorylation but decreased Cdc25c protein level in bladder cancer cells." (PMID 31391858, 2019). "Importantly, CDC25C is also overexpressed in basal tumor subtypes identified by existing classification systems proposed for clinical bladder cancers." (PMID 27775025, 2016). "We characterized CDC25C as a novel prognostic marker in human bladder cancer, which may prove useful for the selection of patients at high risk for treatment failure." (PMID 27775025, 2016). "ATR-1 inhibited bladder cancer cell proliferation, arrested cell cycle in G2/M phase through up-regulation of p21 and down-regulation of cyclin B1, CDK1 and Cdc25c." (PMID 26931119, 2016). "In addition, in a bladder cancer PDX, the overexpression of cell division cycle 25C (CDC25C) has been shown to be a predictive biomarker and is therefore a novel molecular target." (PMID 39329017, 2024). "Atractylenolide I, an active sesquiterpene component extracted from Rhizoma atractylodis, inhibits T24 bladder cancer cell proliferation by arresting the cell cycle in the G2/M phase via downregulation of cell cycle-related proteins such as CDK1, cell division cycle 25C (CDC25c), and cyclin B1." (PMID 33996570, 2021). "We found cell division cycle 25C (CDC25C) overexpression in poorly differentiated BTCs and determined that CDC25C expression predicts adverse survival independent of standard clinical and pathologic features in bladder cancer patients." (PMID 27775025, 2016). "We report cell division cycle 25C (CDC25C) is overexpressed in poorly differentiated bladder tumor cells (BTCs) and predictive of adverse survival after radical cystectomy independent of clinical and pathologic factors in three bladder cancer data sets comprising approximately 400 patients." (PMID 27775025, 2016).
ovarian carcinoma (10 papers, 2010 to 2024). A malignant neoplasm originating from the surface ovarian epithelium. "In the present study, we demonstrated that kaempferol induced G2/M cell cycle arrest via the Chk2/Cdc25C/Cdc2 pathway and Chk2/p21/Cdc2 pathway in human ovarian cancer A2780/CP70 cells." (PMID 29734760, 2018). "Differential regulation of these pathways suggests that ACFP inhibits ovarian cancer cell growth by inhibiting anti-apoptotic protein Bcl-xl, Akt, CDC25C and cyclinB1 and promoting pro-apoptotic protein Bax and Caspase-3." (PMID 27012847, 2016). "Gene expression profiling highlighted that ACFP treatment in ovarian cancer cells repressed the expression of bcl-xl, akt, CDC25C and cyclinB1 and promoted the expression of bax and caspase-3 in a time- and dose-dependent manner." (PMID 27012847, 2016). "Real-time PCR experiments were performed using bcl-xl-, bax-, akt-, caspase-3-, CDC25C- and cyclinB1-specific primers to assess their relative mRNA expressions (2-ΔΔCt) in human primary ovarian cancer cells treated with ACFP for 48 h." (PMID 27012847, 2016). "In parallel, ERK-MAP kinases are shown to be at least in part involved in regulating Cdc25C during mitotic induction in ovarian cancer A2780 cells." (PMID 23637932, 2013). "A recent study based on ovarian cancer reported that kaempferol plays a role in the management of ovarian cancer through the regulation of the cell cycle as kaempferol-induced G2/M cell cycle arrest through the Chk2/p21/Cdc2 pathway and Chk2/Cdc25C/Cdc2 pathway." (PMID 38731498, 2024). "The expression of ITM2A induced G2/M cell cycle arrest and inhibited ovarian cancer cell growth by decreasing the expression of cyclin B1, p-CDC2, CDC2, and CDC25C." (PMID 32300605, 2020). "Western blot analysis was used to demonstrate that treatment of human primary ovarian cancer cells with ACFP at different concentrations for 48 h led to dose-dependent changes in Bcl-xl, Bax, Akt, Caspase-3, CDC25C and CyclinB1 protein levels." (PMID 27012847, 2016). "Gene expression profiles of ovarian cancer cells treated with ACFP were generated by cDNA microarray, and the expression of apoptotic-specific genes, such as bcl-xl, bax, akt, caspase-3, CDC25C and cyclinB1, was assessed by real time PCR and western blot analysis." (PMID 27012847, 2016). "Protoapigenone exhibits a substantial cytotoxic potential on human ovarian cancer cells by inhibition of SKOV-3 and MDAH-2774 cells at the G2/M and S phases of the cell cycle by lowering the expression of p-cyclin B1, cyclin B1, p-Cdk2, and Cdk2 and boosting the inactive p-Cdc25C expressions." (PMID 36386196, 2022). "Because baicalein significantly activates the ATM/CHK2/CDC25C signaling axis, which may lead to G2/M arrest, we next determined whether blocking CHK2 could attenuate baicalein-induced G2/M arrest to confirm the role of CHK2 activation in baicalein-mediated G2/M arrest in ovarian cancer cells." (PMID 36770705, 2023).
colorectal cancer (9 papers, 2014 to 2024). A primary or metastatic malignant neoplasm that affects the colon or rectum. "Many studies have shown that CDC25C is highly expressed in lung, liver, gastric, bladder, prostate, esophageal, and colorectal cancers and in acute myeloid leukemia, correlated to poor prognosis and low survival rates." (PMID 32518522, 2020). "Here, the authors show that ARID1A has a synthetic lethal interaction with AURKA in colorectal cancer cells and that ARID1A deficiency activates the AURKA target CDC25C, whose inhibitors also cause cell death in the ARID1A-deficient cell lines." (PMID 30097580, 2018). "Increased caspase-9 and -3 protein cleavage, and cyclin B1 and cdc25c proteins through induction of JNK protein phosphorylation by EVO were observed in colorectal carcinoma cells." (PMID 24959718, 2014). "Furthermore, EVO and its structurally related compounds including EVO-4, -5, and -8 were used to study the effects on caspase-3, PARP, cyclinB1, and cdc25c protein expressions with cell cycle progression in both colorectal carcinoma cell lines." (PMID 24959718, 2014). "Our results showed that CYT-Rx20 induced G2/M arrest in colorectal cancer cells with upregulated expression of cyclin B1, aurora A, and aurora B, and downregulated expression of cdc25A and cdc25C, which collectively could contribute to the inactivation of cdc2." (PMID 28178649, 2017). "In addition, CYT-Rx20 induced cell cycle arrest of colorectal cancer cells at the G2/M phase and upregulated the protein expression of phospho-ERK, cyclin B1, phospho-cdc2 (Tyr15), aurora A, and aurora B, while it downregulated the expression of cdc25A and cdc25C." (PMID 28178649, 2017).
cervical cancer (7 papers, 2015 to 2023). A primary or metastatic malignant neoplasm involving the cervix. "Moving to other types of human tumors, RACGAP1 was able to promote melanoma transendothelial migration through mediating adherens junction disassembly and promoted proliferation and cell cycle progression by regulating CDC25C in cervical cancer cells." (PMID 36430577, 2022). "The results showed that SB down-regulated the expressions of CDK1, cyclin B1, and cdc25C at protein levels, which further suggests that SB induces G2/M cell cycle arrest in cervical cancer cells." (PMID 32226384, 2020). "Endogenous FHL1 interacted with endogenous CDC25C, from both cytoplasmic and nuclear fractions of cervical cancer HeLa cells, in the absence or presence of IR." (PMID 28094252, 2017). "In the present study, we found that SB induced cell cycle arrest at G2/M phase and reduced the protein expressions of cdc25C, CDK1, and cyclin B1 in cervical cancer cells, which may be the mechanism of action underlying the SB-inhibited cervical cancer cell proliferation." (PMID 32226384, 2020). "Our results showed that Drp1-knockdown in cervical cancer cells reduced the G2/M cell cycle arrest and reversed the reduction of CDK1, cyclin B1 and cdc25C expressions compared to control cells upon SB treatment." (PMID 32226384, 2020). "By controlling CDC25C, RACGAP1 encourages the growth of cervical cancer cells." (PMID 37391503, 2023). "The inhibition of cervical cancer cell proliferation induced by SB may due to the increased expression of Drp1, which reduced CDK1, cyclinB1, and cdc25C expressions in G2/M cell cycle arrest." (PMID 32226384, 2020).
gastric cancer (7 papers, 2012 to 2024). A primary or metastatic malignant neoplasm involving the stomach. "Kaempferol led to a noticeable decrease in the protein levels of cyclin B1, Cdc25C and Cdk1 in a dose-dependent manner in gastric cancer cells." (PMID 37239974, 2023). "In human gastric cancer cells, suppressing the expression of Cdc25C would promote the cyclin B1/CDK1 complex and result in G2/M arrest." (PMID 35628435, 2022). "Our data suggest that the inhibition effect of FKB on gastric cancer cell growth may be related to the regulation of cell cycle-related proteins including cyclin A, cyclin B1, Cdc2, and Cdc25C." (PMID 35879950, 2022). "Luteolin has been reported to reduce the levels of the CDC25c, CDC2, and cyclin B1 proteins and induces G2/M phase arrest in human gastric cancer cell lines." (PMID 22269172, 2012).